IL13RA2 (interleukin 13 receptor subunit alpha 2)
Diseases named in the same sentence as IL13RA2 in open-access papers (continued):
Sharing a sentence is not in itself a finding about the gene and the disease.
glioblastoma (continued). "It has been reported that IL13Rα2 overexpression promotes glioblastoma tumor progression and as the malignancy grade of glioblastoma increases the IL13Rα2 expression is promoted accordingly." (PMID 35612318, 2022). "In comparison to normal brain tissues, glioblastoma is overexpressed with certain type of cytokine receptors known as IL13Rα2 that exhibit high affinity for IL-13." (PMID 35612318, 2022). "IL13RA2, one of the high-affinity membrane receptors of IL-13, is highly expressed in tumors, such as liver cancer, glioblastoma, colon cancer, and pancreatic cancer." (PMID 35770008, 2022). "This trial evaluated a first-generation CAR targeted the interleukin-13 receptor alpha 2 (IL13Rα2) on glioblastoma cells." (PMID 33753869, 2022). "Glioblastoma-derived cells in vitro demonstrated expression of IL13Rα2, EphA2 and Fra-1, described previously as AAAs (astrocytoma-associated antigens) facilitating tumor culture establishment." (PMID 33245508, 2022). "Bi-specific CAR T-cells targeting both HER2 and IL13Rα2 resulted in increased tumor elimination as compared with CAR T-cells targeting a single antigen in a murine model of glioblastoma." (PMID 35692797, 2022). "Finding a potential target in glioblastoma treatment, the extensively studied and versatile target is IL-13 receptor α2 (IL13Rα2) and it is attributed to its selective and high expression on glioblastoma." (PMID 35612318, 2022). "Noticeably, IL13Rα2 cooperates with epithermal growth factor receptor (EGFR) VIII signaling to promote glioblastoma multiforme, whereas PDGF receptor (PDGFR)β plays an essential role in vitreous-induced cellular responses related to PVR." (PMID 35770008, 2022). "It is believed that IL13Rα2 is related to poor survival and highly expressed in glioblastoma stem cells." (PMID 35612318, 2022). "Tri-specific CAR T-cells targeting HER2, IL13Ra2, and EphA2 achieve a wider coverage of antigens, and studies have shown that this strategy prolongs the survival of mice bearing glioblastoma patient-derived xenografts." (PMID 35692797, 2022). "Human epidermal growth factor receptor 2 (HER2), interleukin-13 receptor subunit alpha-2 (IL13Rα2), and ephrin-A2 (EphA2) are specifically expressed on the surface of glioblastoma, recurrent medulloblastoma, and ependymoma cells." (PMID 35410257, 2022). "In the field of glioblastoma research, IL13Rα2 has been extensively studied and thoroughly investigated tumor specific antigen and glioma specific marker." (PMID 35612318, 2022). "In a phase I study, recurrent glioblastoma and refractory glioblastoma were treated with CAR-T cells that have a high affinity to TAA interleukin-13 receptor α 2 (IL-13Rα2), which is overexpressed in recurrent glioblastoma." (PMID 34485282, 2021). "The signaling pathway through IL-13Rα2 in glioblastoma multiforme was also examined in our laboratory." (PMID 34201539, 2021). "It has been reported that IL13Rα2 was overexpressed in various cancers, such as glioblastoma, metastatic colorectal cancer, and ovarian cancer, which suggests that IL13Rα2 can play crucial roles in the development of various cancer types." (PMID 33917914, 2021). "IL-13Rα2 is highly expressed in various solid cancers, including pancreatic cancer, glioblastoma, ovarian cancer, breast cancer, colon cancer, prostate cancer, melanoma, and so on." (PMID 34201539, 2021). "Hsi and coworkers demonstrated that IL-13Rα2 knockdown with siRNA dramatically induced 15-lipoxygenase-1 expression, promoted apoptosis, and reduced tumor growth in glioblastoma." (PMID 33804263, 2021). "In solid tumors, several tandem CARs have been tested in preclinical models including HER2 and IL13Ra2 in glioblastoma and HER2 and MUC1 in breast cancer." (PMID 33824268, 2021). "We have previously reported that IL-13Rα2 is overexpressed in several types of cancer including renal cell carcinoma, glioblastoma multiforme, ovarian cancer, colorectal cancer and pancreatic cancer." (PMID 33591997, 2021).
glioblastoma (continued). "For example, a CAR-T cell therapy case report that targeted IL13Ra2 in glioblastoma suggested that tumor recurrences displayed decreased IL13Ra2 expression." (PMID 33824268, 2021). "There are several ongoing CAR T cell candidates for glioblastoma including CARs directed against EGFRvIII, IL13Rα2 and HER2." (PMID 34054867, 2021). "A study utilized 89Zr-oxine for labeling anti-IL13Rα2 CAR T cells that targeted glioblastoma multiforme (GBM) cells." (PMID 33391977, 2021). "In orthotopic mouse models of glioblastoma and malignant melanoma, they showed that [64Cu]Pep-1L selectively binds to IL-13Rα2-expressing G48 tumors revealing intra-cranial IL-13Rα2-expressing glioblastoma." (PMID 34201539, 2021). "Several important breakthroughs have been reported recently, especially with adult brain tumors, where a transient yet complete remission in a patient with disseminated glioblastoma (GBM) treated with IL13Rα2-specific CAR T cells has been reported." (PMID 34771608, 2021). "The described response of a glioblastoma to IL13Rα2-targeted CAR-T was achieved after intracranial delivery." (PMID 33874996, 2021). "Interleukin-13 receptor alpha-2 (IL-13Rα2), the high-affinity receptor for IL-13, is frequently overexpressed in the majority of glioblastoma multiforme (GBM) tumors in comparison to normal healthy brain tissue." (PMID 35011583, 2021). "A similar down-regulation of the target has also been reported in one patient who underwent surgery after treatment with IL13Ra2-targeting CAR-T cells for glioblastoma." (PMID 33874996, 2021). "Preclinical successes using bispecific CAR-T cells have been reported in solid tumors, including the use of a tandem CAR against Her2/IL13Rα2 in a murine glioblastoma model." (PMID 32244520, 2020). "Pooled CAR-T cells targeting HER2/IL-13Rα2 for glioblastoma (GBM), CD19/CD123 for B-ALL, and EGFR/CD133 have been tested in preclinical studies and showed some benefits as well as some disadvantages." (PMID 33207607, 2020). "IL-13Rα2 is one of the specific markers for glioblastoma (GBM) malignant cells that have a key role in disease prognosis." (PMID 33167514, 2020). "A recurrent glioblastoma patient received intracranial infusion of IL13Rα2 CAR-T followed by infusions in the ventricular system." (PMID 31979318, 2020). "Clinical trials demonstrating the benefit IL13Rα2 CAR T-cells in the treatment of glioblastoma are currently underway." (PMID 38572351, 2020). "IL13Rα2 is a high affinity IL-13 receptor that is overexpressed in glioblastoma, including glioblastoma stem cells, and it is related to poor survival." (PMID 31979318, 2020). "Trivalent CAR T cells targeting three glioblastoma associated antigens (HER2, IL-13Rα2-, and EphA2-specific CAR molecules, all expressed simultaneously on the T cell surface) are now designed." (PMID 32235752, 2020). "Intracranial infusion of an IL13Rα2-targeting CAR-T product in a patient with recurrent multifocal glioblastoma resulted in regression of all intracranial and spinal tumors, accompanied by increased immune cells in the cerebrospinal fluid." (PMID 32244520, 2020). "In the treatment of solid tumors, grade 1–2 neurotoxicity was reported in treatment of glioblastoma with IL13Rα2 CAR T-cells." (PMID 38572351, 2020). "In summary, we provide strong evidence that PTP1B inhibition is a promising strategy for cancers overexpressing IL13Rα2, such as advanced colorectal, ovarian, and glioblastoma, among others." (PMID 32098194, 2020). "IL13RA2 is often overexpressed in glioblastoma multiforme (GBM), and expression is correlated with poor patient outcome." (PMID 32983080, 2020). "Reactive astrocytes of the tumor environment released CHI3L1, which drives MAPK and AKT signaling in glioblastoma via stimulation of IL13Rα2." (PMID 31561550, 2019). "This strategy has been investigated, such as pooling monospecific CAR-T cells targeting human epidermal growth factor receptor-2 (HER2)/IL-13Rα2 for glioblastoma and CD19/CD123 for B-ALL." (PMID 31783889, 2019).
glioblastoma (continued). "Intriguingly, the same group later reported regression of recurrent multifocal glioblastoma in one patient following anti-IL13Rα2-CAR T cell therapy." (PMID 31108883, 2019). "Till date, EGFRVIII, HER2, and IL-13Rα2-expressing CAR-T cells have been applied in clinical studies of glioblastoma and have shown promising results in a few patients." (PMID 31288857, 2019). "The resulting IL-13Rα2-specific ε-TRuC-T cells lysed target-positive U251 glioblastoma cells at various effector-to-target ratios and caused release of IFN-γ and IL-2 by T cells." (PMID 31064990, 2019). "To investigate a broader utility of TRuC-T cells, we generated TRuC-T cells using antibody domains specific for the multiple myeloma target B Cell Maturation Antigen (BCMA) and for the glioblastoma multiforme (GBM) target interleukin-13 receptor α2 (IL-13Rα2)." (PMID 31064990, 2019). "Combined expression of EphA2, EphA3, EphB2, and IL-13RA2 is observed in almost 100% of patients with glioblastoma patients." (PMID 30366424, 2018). "To date, the clinical outcomes of 5 patients receiving intrathecally or intracranially delivered IL-13Rα2 targeting CAR T cells for glioblastoma have been reported." (PMID 30467505, 2018). "Despite a growing list of clinical studies, remarkable responses have been rarely achieved with the exception of a case in glioblastoma with intraventricular delivery of the IL13Rα2 CAR." (PMID 30416506, 2018). "Next, we investigated the effect of the D1 peptide on the downstream IL-13/ IL13Rα2 signalling in colorectal and glioblastoma cell lines." (PMID 30318506, 2018). "For example, in a recent clinical trial, multiple intracranial injections of CAR-T targeting IL13Rα2 mediated a transient complete response in a patient with glioblastoma." (PMID 30405639, 2018). "In a study conducted by Brown and colleagues, regional, multi-dose treatment with IL13Rα2 specific CAR T cells induced a complete remission in a patient with disseminated glioblastoma." (PMID 30467505, 2018). "Previously, we have demonstrated that Interleukin 13 receptor alpha 2 (IL-13Rα2) is overexpressed in approximate 78% Glioblastoma multiforme (GBM) samples." (PMID 30572904, 2018). "A case report of IL13RA2-targeted chimeric antigen receptor T-cell therapy showed regression of glioblastoma in a human patient." (PMID 29621254, 2018). "This is consistent with previous research showing the potential of IL-4 and IL-13Rα2 as potential therapeutic targets in pediatric brain tumors such as glioblastoma." (PMID 29621254, 2018). "Despite advances in the understanding of IL-13Rα2 biology in glioma tumors and clinical trials targeting this receptor for therapy, the functional significance of IL-13Rα2 expression in malignant glioblastoma is not well understood." (PMID 29168083, 2018). "A case study of a patient with recurrent multifocal glioblastoma who was given multiple infusions of CAR T-cells engineered to target interleukin-13 receptor alpha 2 (IL13Rα2) showed good tolerance and regression of intracranial and spinal tumours." (PMID 29570634, 2018). "A remarkable response was observed in a single glioblastoma patient following multiple IL13Rα2 CAR T cell infusions (intratumor resected cavity and intra-ventricular), lasting 7.5 months." (PMID 30279357, 2018). "A clinical trial of autologous CAR T cells targeting IL13Rα2 provided the first evidence for a CAR T cell−mediated CR to therapy in glioblastoma." (PMID 29312333, 2017). "There was one case report in the literature on rapidly progressing refractory glioblastoma that showed dramatic CR to IL13Rα2-targeted CAR-T cells after repeated infusion." (PMID 29058636, 2017). "CAR T cell targeting of the tumor antigen IL13Rα2 in patients with glioblastoma has encountered similar hurdles with antigen heterogeneity." (PMID 29312333, 2017).
glioblastoma (continued). "This disease-associated expression profile supports the development of CAR T cells targeting IL13Rα2 for the treatment of glioblastoma and possibly other solid tumors." (PMID 29312333, 2017). "Preclinical experiments with trivalent CAR T cells co-targeting HER2, IL13Rα2, and EphA2 showed promise in overcoming glioblastoma variability." (PMID 29312333, 2017). "Interluekin-13 receptor alpha 2 (IL13RA2) is a glioblastoma restricted receptor that is abundantly overexpressed in over 75% of GBMs but absent in normal brain tissue, highlighting its potential as a therapeutic target against GBM." (PMID 28562337, 2017). "Recently, a patient suffering from multifocal glioblastoma has also shown regression of all intracranial and spinal tumors after treatment with IL-13Rα2 specific CAR T cells." (PMID 29203859, 2017). "We radiolabeled Pep-1L with Copper-64 and demonstrated specific cell uptake in the IL13RA2-over expressing G48 glioblastoma cell line having abundant IL13RA2 expression." (PMID 28881623, 2017). "In the course of these experiments, we unexpectedly found that the commercially available putative IL13Rα2-specific monoclonal antibody B-D13 recognizes cytokine-induced VCAM-1 on glioblastoma." (PMID 24787244, 2014). "Interleukin 13 receptor alpha 2 (IL-13RA2) is over-expressed in a vast majority of human patients with high-grade astrocytomas like glioblastoma." (PMID 24147065, 2013). "IL-13-PE was used in a Phase 3 clinical study to treat patients with glioblastoma multiforme, another cancer type wherein IL-13Rα2 is overexpressed in the majority of tumor cells." (PMID 23421960, 2013). "Several isolated MAbs were immunoreactive to IL-13RA2 in western blots of cell and tissue lysates from glioblastomas from both human and canine patients." (PMID 24147065, 2013). "We also cultivated Human Glioblastoma cells, and measured the electrophoretic mobility of the cells which had been reacted with anti-IL13RA2." (PMID 21206908, 2010). "For instance, tandem anti-HER2 and IL13Rα2 CAR-NK cells exhibited a 40% increase in cytotoxic efficiency against dual-antigen–positive cells compared with single-antigen CARs in glioblastoma models, while also markedly decreasing the probability of therapeutic failure associated with antigen loss." (PMID 41488873, 2025). "An independent randomized double-blind phase II trial involving a larger cohort of glioblastoma patients led to comparable conclusions using autologous DCs pulsed with six synthetic peptide epitopes derived from glioblastoma-associated antigens MAGE-1, IL13Rα2, AIM-2, TRP-2, gp100, and HER-2." (PMID 41514632, 2025). "Preclinical studies on murine models have demonstrated that the intraventricular delivery of CAR-T cells is highly efficient in targeting human epidermal growth factor receptor 2 (HER2) and interleukin-13 receptor subunit alpha-2 (IL13Rα2) in breast cancer brain metastases and glioblastoma." (PMID 40906384, 2025). "A landmark case demonstrated a complete response in recurrent multifocal glioblastoma during a clinical trial using multiple intracavitary and intraventricular infusions of IL13Rα2-specific CAR-T cells, highlighting the viability of repeated locoregional treatment." (PMID 40906384, 2025). "IL13RA2 is enhanced in multitudinous patients with glioblastoma." (PMID 39220137, 2024). "Similarly, intrathecal bivalent CAR-T cells targeting EGFR and IL13Rα2 in recurrent glioblastomas reported interim results showing manageable toxicity and encouraging progression-free survival." (PMID 38892305, 2024). "In addition, higher expression of IL-13Rα2 has also been reported in several types of cancer, including glioblastoma, ovarian carcinoma, head and neck cancer, melanoma, and colorectal cancer." (PMID 39598436, 2024). "Targeting IL13RA2 is a potential therapeutic approach for glioblastoma." (PMID 39220137, 2024).
glioblastoma (continued). "In a different trial, glioblastoma patients received CART-EGFR-IL13Rα2 cells targeting both EGFR and IL13Rα2 intrathecally through an intraventricular reservoir, leading to a transient regression of the tumor in all patients and early persistence of CAR T cells in the CSF." (PMID 39199630, 2024). "IL-13Rα2 stimulated cancer progression in glioblastoma by activating the AP-1 pathway." (PMID 39598436, 2024). "In glioblastoma, high IL13RA2 expression predicts worse prognosis." (PMID 39220137, 2024). "Constructed CARs with a single universal tricistronic transgene were designed to recognize three different TAAs, namely, human epidermal growth factor receptor 2 (HER2), interleukin-13 receptor subunit alpha-2 (IL13Rα2), and ephrin-A2 (EphA2) to treat glioblastoma." (PMID 39835140, 2024). "A trial of personalized CAR T cells against one of the common glioblastoma targets, including EGFRvIII, IL13Ra2, HER2, EphA2, CD133, and GD2, has published initial results for a cohort of three patients who received EphA2-CART administered in a single dose intravenously." (PMID 37754534, 2023). "Interleukin IL-13 is expressed in glioblastoma; it binds to two receptors, IL-13Rα1 and IL-13Rα2, and mediates a variety of different effects on various cell types, including B cells, neutrophils, monocytes, natural killer cells, endothelial cells, and fibroblasts." (PMID 38003396, 2023). "Of these potential targets, IL13Rα2 has been one of the most extensively studied and may be a promising candidate due to the fact that it is expressed at much higher levels in glioblastoma compared to normal brain cells." (PMID 38132354, 2023). "All CAR-Ts killed glioblastoma cells with high levels of IL13Rα2 expression." (PMID 37563127, 2023). "This reduction in IL-13Rα2 expression is potentially explained by the findings of previous studies in that the central layers of multi-cellular spheroids were shown to be hypoxic and, notably, IL-13Rα2 mRNA expression in glioblastoma cells was reportedly decreased under hypoxic conditions." (PMID 37345109, 2023). "Over the years, researchers have identified unique markers in glioblastoma such as the epidermal growth factor receptor variant III (EGFRvIII), human epidermal growth factor receptor 2 (HER2) and IL-13 receptor alpha 2 (IL-13Rα2) as unique targets of CAR-T therapy." (PMID 37046685, 2023). "However, a recent study identified a novel IL-13Rα2-targeted hybrid lytic peptide for effective therapy for glioblastoma, which has also been shown to overexpress IL-13Rα2." (PMID 36830725, 2023). "IL-13Rα2 is often overexpressed in malignant tumors, especially in glioblastoma multiforme (GBM)." (PMID 37429945, 2023). "Moreover, CAR-T cells targeting 3 glioblastoma associated antigens (HER2, IL13Rα2, and EphA2) were also developed and showed even more effectiveness as compared to the bispecific CAR-T." (PMID 35603195, 2022). "Although IL13Ra2 is expressed in 80% of glioblastomas and could thus be an ideal target, it is overexpressed in only 44–58% of glioblastomas." (PMID 35692797, 2022). "The solid tumors involved in these articles mainly include glioblastoma (related targets: IL13Rα2, EGFRvIII, and HER2), neuroblastoma (related target: GD2), sarcoma (related target: HER2), and pancreatic cancer (related target: mesothelin), especially glioblastoma." (PMID 35371087, 2022). "The functional significance of IL13Rα2 in glioblastoma is still controversial that needs further investigations; however, poor prognosis and refractory mesenchymal phenotype manifest its expression in glioblastoma." (PMID 35612318, 2022). "While in glioblastoma multiform, IL13Rα2 offers expression for about 30,000 binding sites." (PMID 35612318, 2022). "Pep‐1L, an IL‐13Rα2 targeting peptide, reduces glioblastoma development." (PMID 34758182, 2022). "An example is TanCAR-T cells binding either HER2 or IL13Rα2 in glioblastoma cells." (PMID 35326556, 2022).